SGPP1 (sphingosine-1-phosphate phosphatase 1)
Diseases named in the same sentence as SGPP1 in open-access papers:
SGPP1 is named in the same sentence as 37 diseases in open-access papers, as found by Europe PMC text mining. Sharing a sentence is not in itself a finding about the gene and the disease. The quoted sentences say what the papers report.
gastric cancer (6 papers, 2017 to 2022). A primary or metastatic malignant neoplasm involving the stomach. "In vitro experiments showed that knockdown of SGPP1 increased invasiveness and migration of gastric cancer cells." (PMID 35158806, 2022). "A comparison of gastric cancer and normal tissue specimens showed that gastric cancer tissue generally had reduced sphingosine-1-phosphate phosphatase 1 (SGPP1)." (PMID 35158806, 2022). "In gastric cancer tissues, the expression of SGPP1 was down-regulated compared with adjacent tissues and cancer-free tissues." (PMID 36059802, 2022). "It was confirmed that the low expression of SGPP1 was positively correlated with the distant metastasis of lymph nodes and gastric cancer." (PMID 36059802, 2022). "A positive connection between the low expression of SGPP1 and lymph node and distant metastasis of gastric cancer were confirmed." (PMID 35081855, 2022). "In gastric cancer tissues, the SGPP1 expression is downregulated compared to that in adjacent and cancer-free tissues." (PMID 35081855, 2022). "SGPP1 is downregulated in gastric cancer and plays a role in invasion and migration in gastric cancer cells." (PMID 34235182, 2021). "SGPP-1 is downregulated in human gastric cancer tissues and plays a role in invasion and migration in gastric cancer cells." (PMID 29375197, 2017). "Similarly, SGPP1 was downregulated in gastric cancer tissues, and knockdown of SGPP1 resulted in an increase in the invasion of human gastric carcinoma cell lines." (PMID 34073605, 2021).
colorectal cancer (5 papers, 2014 to 2023). A primary or metastatic malignant neoplasm that affects the colon or rectum. "miR-656-3p could regulate cell proliferation and chemoresistance in the colorectal cancer that associate to downstream target with SGPP1." (PMID 35081855, 2022). "Recently, more comprehensive investigation approved that SGPP can deeply associate with calcium signaling pathway which may provide more effective prospects on unveiling miRNA-656-3p associated SGPP1 mechanism in colorectal cancer." (PMID 35081855, 2022). "Studies have shown that the expression of SGPP1 is low in colorectal cancer and is correlated with tumor proliferation, migration, and invasion." (PMID 37521466, 2023). "Some studies have demonstrated that SGPP1 was the target in the carcinogenesis and progression of colorectal cancer." (PMID 36843983, 2023). "The result provides strong potential for developing miR-656-3p- SGPP1 as treatment against colorectal cancer." (PMID 35081855, 2022). "As SGPP1 and Smad2 were likely the targets of miR-27a, we then determined the expression levels of SGPP1 and Smad2 in human colorectal cancers and cancer cell lines." (PMID 25166914, 2014). "SGPP1 and Smad2 at mRNA and protein levels were negatively correlated with miR-27a in human colorectal cancer tissues and cancer cell lines." (PMID 25166914, 2014). "The expression of SGPP1 and Smad2 were then evaluated in human colorectal cancers by immunohistochemical staining." (PMID 25166914, 2014). "Both SGPP1 and Smad2 mRNA levels were inversely correlated with the miR-27a levels at these human colorectal cancer cells." (PMID 25166914, 2014). "Compared to the adjacent normal colon mucosa, both SGPP1 and Smad2 expression were much higher at colorectal adenocarcinomas, negatively correlated with miR-27a levels in colorectal cancers in which miR-27a was frequently reduced." (PMID 25166914, 2014). "Using the approaches of miRNA array, systemic biology, in vitro manipulating expression of miR-27a and in vivo tumor-bearing mouse model, we found that miR-27a acted as a tumor suppressor in colorectal cancer, which was through targeting SGPP1 and Smad2." (PMID 25166914, 2014). "Therefore, miR-27a could be a useful biomarker for monitoring colorectal cancer development and progression, and also could have a therapeutic potential by targeting SGPP1, Smad2 and STAT3 for colorectal cancer therapy." (PMID 25166914, 2014). "Therefore, miR-27a could be a useful biomarker for colorectal cancer development and progression, and also could have a therapeutic potential targeting SGPP1, Smad2 and Stat3 for colorectal cancer therapy." (PMID 25166914, 2014). "SGPP1 and Smad2 protein levels were also downregulated by miR-27a on both HCT116 and SW480 colorectal cancer cells." (PMID 25166914, 2014). "Taken together, this study has revealed miR-27a as a tumor suppressor and has identified SGPP1 and Smad2 as novel targets of miR-27a, linking to STAT3 for regulating cancer cell proliferation, apoptosis and migration in colorectal cancer." (PMID 25166914, 2014).
breast carcinoma (4 papers, 2019 to 2023). "In addition, our study found that SGPP1 expression in breast cancer was associated with neutrophils, macrophages, CD4+ and CD8+ cells." (PMID 37521466, 2023). "For instance, increased expression of miR-95 in human breast cancer specimens indicates the resistance to radiation treatment by targeting sphingosine-1-phosphate phosphatase 1 (SGPP1), an antagonist of sphingosine-1-phosphate signaling in TNBC cells." (PMID 31766744, 2019). "Correlation between mRNA expression of SGPP1 and PLPP3 with relapse-free survival in the different breast cancer intrinsic subtypes." (PMID 34235182, 2021). "Correlation between mRNA expression of SGPP1 and PLPP3 with relapse-free survival in the breast cancer patients with ER, PR, HER2 and LN status." (PMID 34235182, 2021). "Correlation between mRNA expression of SGPP1 and PLPP3 with relapse-free survival (RFS) in the systemically treated in different breast cancer intrinsic subtypes." (PMID 34235182, 2021). "For breast cancer, we present an interaction between SPRY2 and C0L10A1 and for kidney one between TFAP2A and SGPP1." (PMID 32859146, 2020).
myeloma (3 papers, 2021 to 2022). "An earlier study has shown that transcriptional repressor GFI1 negatively regulates the expression of SGPP1 and that GFI1-dependent SGPP1 repression promotes growth and survival of multiple myeloma cells." (PMID 34235182, 2021).
diabetes (2 papers, 2014 to 2017). "The level of SPL was decreased 1.6 fold and the levels of SGPP1 and SGPP2 were also decreased 4.8 fold and 15.7 fold separately in diabetes compared with control subjects." (PMID 24751283, 2014).
non-small cell lung carcinoma (2 papers, 2021 to 2022). A group of at least three distinct histological types of lung cancer, including non-small cell squamous cell carcinoma, adenocarcinoma, and large cell carcinoma. "Moreover, expression of SGPP1 and PLPP3 was associated with overall survival in lung adenocarcinoma and non-small-cell lung carcinoma (NSCLC) patients, where expression of PLPP3 correlated with tumor-infiltrating immune cells in NSCLC patients." (PMID 35163211, 2022). "SGPP1 has also been shown to be a target of miR-95, which is highly expressed in ALDH+ and CD133+ subpopulations of non-small cell lung cancer (NSCLC) compared to ALDH1- and CD133-cells." (PMID 34235182, 2021).
triple-negative breast carcinoma (2 papers, 2021 to 2023). An invasive breast carcinoma which is negative for expression of estrogen receptor (ER), progesterone receptor (PR), and human epidermal growth factor receptor 2 (HER2). "Similarly, low expression of SGPP1 in triple-negative breast cancer strongly correlates with poor prognosis." (PMID 37521466, 2023). "Correlation between mRNA expression of SGPP1 and PLPP3 with relapse-free survival (RFS) in Pietenpol subtypes of triple-negative breast cancer (TNBC)." (PMID 34235182, 2021).
asthma (1 paper, 2024). "Among these genes, ASAH1, ACER3, and SGPP1 were identified as potential diagnostic biomarkers for asthma." (PMID 38297226, 2024). "The MCODE analysis identified a key module in the network, including three hub genes (ASAH1, ACER3 and SGPP1), all of which were downregulated genes and strongly linked to asthma." (PMID 38297226, 2024). "ASAH1, ACER3 and SGPP1 might be diagnostic biomarkers for asthma, and are associated with increased immune system activation." (PMID 38297226, 2024). "Three downregulated LMRGs (ASAH1, ACER3 and SGPP1) were identified as hub genes for asthma, which were validated in GSE143192." (PMID 38297226, 2024). "Nevertheless, the role of SGPP1 in asthma needs to be further confirmed." (PMID 38297226, 2024). "We observed significantly reduced SGPP1 expression levels in asthma patients." (PMID 38297226, 2024). "The low expression of ASAH1 and SGPP1 in asthma was also validated in the GSE74075 dataset." (PMID 38297226, 2024). "Thus, we hypothesized that individuals with downregulated LMRGs (ASAH1, ACER3 and SGPP1) may be liable to mediate the immune response, and more easily develop asthma." (PMID 38297226, 2024). "Therefore, ASAH1 and SGPP1 may be the key genes involved in the occurrence of asthma." (PMID 38297226, 2024).
B cell lymphoma (1 paper, 2017).
breast tumors (1 paper, 2021). "The results showed that the protein levels of PLPP3 and SGPP1 were decreased significantly in primary breast tumors as compared to normal breast tissue." (PMID 34235182, 2021).
cardiac hypertrophy (1 paper, 2025). "Further investigation into the roles of miR-34a, miR-351, and miR-490*, alongside validated genes such as HTR2A, SGPP1, ITGA7, and GANC is essential to elucidate their contributions to early-onset cardiac hypertrophy." (PMID 41468376, 2025).
endometriosis (1 paper, 2022). The growth of functional endometrial tissue in anatomic sites outside the uterine body. "However, gene expression involved in ceramide synthesis (SPHK1, ASAH1, and SGPP1) and autophagy (BECN1, LAMP, and PC3) were significantly lower in MGCs with endometriosis, whereas CERS1 and UGCG expression increased." (PMID 35992117, 2022).
glioblastoma (1 paper, 2016). The most malignant astrocytic tumor (WHO grade IV). "Beside glioblastoma patient samples, we isolated glioblastoma cells from freshly resected tumor tissue of three different patients and analyzed the expression of S1P1-5, SphK1 and 2, SGPP1 and 2 as well as SGPL1 by quantitative RT-PCR." (PMID 26887055, 2016).
hepatocellular carcinoma (1 paper, 2013). A malignant tumor that arises from hepatocytes. "Comparison of normal livers to hepatocellular carcinomas, using four independent sets of samples available in the Oncomine database, revealed significantly decreased levels of ASM (SMPD1) and S1P phosphatase (SGPP1) mRNA expression." (PMID 23724146, 2013).
idiopathic pulmonary fibrosis (1 paper, 2014). Idiopathic pulmonary fibrosis (IPF) is a nonneoplastic pulmonary disease that is characterized by the formation of scar tissue within the lungs in the absence of any known cause. "Limited studies have demonstrated that SGPP1 catalyzes the degradation of S1P via salvage and recycling of sphingosine into long-chain ceramides, and that aberrant expression of SGPP1 is associated with idiopathic pulmonary fibrosis, and pulmonary fibrosis." (PMID 25166914, 2014).
invasive breast carcinoma (1 paper, 2021). A carcinoma that infiltrates the breast parenchyma. "Both of the S1P-catabolizing genes, SGPP1 and PLPP3, showed high predictive value for response to systematic therapy in invasive breast carcinoma patients and especially in the HER2+ and basal subtypes." (PMID 34235182, 2021).
lymphoma (1 paper, 2017). A malignant (clonal) proliferation of B- lymphocytes or T- lymphocytes which involves the lymph nodes, bone marrow and/or extranodal sites. "Together these data indicate that Sgpp1 induction is at least partially responsible for death of lymphoma cells mediated by glucocorticoid signaling." (PMID 27869314, 2017). "Moreover, we show that Runx1 regulates glucocorticoid sensitivity in lymphoma cells and identify an established direct target gene, Sgpp1, as an integrator of sphingolipid metabolism and responses to glucocorticoids." (PMID 27869314, 2017).
neural tube defect (1 paper, 2014). A congenital defect characterized by failure of the neural tube to close completely; this results in the presence of openings in the brain or spinal cord. "We examined the incidence of neural tube defects and weight changes of fetus and placenta, as well as the gene expression of LASS5 (in maternal liver and fetus), Sphk1, Sphk2, Sgpl1, and Sgpp1 in the maternal liver, uterus, fetus, and placenta." (PMID 25383881, 2014).
thymic lymphoma (1 paper, 2017). "Together the data support a mechanism whereby the opposition of Sgpp1 transcription and the overexpression of Ugcg might contribute to Runx1‐induced survival in the presence of dexamethasone in thymic lymphoma cell lines." (PMID 27869314, 2017).
tumor (12 papers, 2014 to 2025). "The mRNA expression of SGPP1 was also associated with tumor DCs in the other cancer types." (PMID 34235182, 2021). "The results of ANKRD52 level expressed that the HOXC10, KNOP1, and TRIM45 in the tumor tissue were higher in the paracancerous tissue, and the opposite was true for SGPP1." (PMID 37521466, 2023). "The transplanted tumor model was established to investigate the role of SGPP1 siRNA in regulating tumor growth." (PMID 35081855, 2022). "Knockdown of SGPP1 greatly suppressed the tumor growth in vivo and epithelial mesenchymal transition process." (PMID 35081855, 2022). "In addition to its involvement in ESCC, miR-27a acted as a tumor suppressor in colorectal carcinogenesis and progression by targeting SGPP1 and Smad215." (PMID 26980408, 2016). "So it might be possible that the locally produced S1P attracts immune cells into the tumor region to attack the malignant cells being enhanced by a low expression of SGPP1 and thus higher S1P levels." (PMID 26887055, 2016). "The mechanistic studies further showed that miR-27a-mediated tumor suppressor could be through targeting SGPP1, Smad2 and STAT3." (PMID 25166914, 2014). "We selected 4 candidate genes (PCSK9, SGPP1, PGK1 and FOXM1) reported to be closely involved in tumour progression and radioresistance for further analysis." (PMID 39548064, 2024). "We have determined the protein expression of four S1P-metabolizing enzymes (SphK1, SphK2, sphingosine-1-phosphate phosphatase 1 (SGPP1), and lipid phosphate phosphatase 3 (LPP3)) by immunohistochemistry (IHC) in tumor tissues of 46 OSCC patients." (PMID 35494957, 2022). "We demonstrated herein that the expression of SGPP1, PLPP3, and S1P receptors, particularly S1PR4, positively correlates with tumor-infiltrating DCs in TNBC." (PMID 34235182, 2021). "SGPP1 and PLPP3 expression show a strong positive correlation with tumor-infiltrating dendritic cells (DCs), CD4+ and CD8+ T cells, neutrophils, and macrophages in the TNBC subtypes." (PMID 34235182, 2021). "Of particular interest, Sgpl1 and Sgpp1, key enzymes involved in the metabolism of S1P, were significantly downregulated across all hepatic cells in the HCC group but increased in hepatocytes, HSCs, ECs, immune cells, and macrophages in the pre-tumor group." (PMID 40057751, 2025). "Since no information is available regarding immunohistochemical localization of SphK2, SGPP1, and LPP3 in OSCC, thus, in the present study, we have analyzed the expression of SphK1, SphK2, SGPP1, and LPP3 in tumor tissues from OSCC patients and benign oral mucosa by immunohistochemistry (IHC)." (PMID 35494957, 2022). "We, therefore, conclude that low expression of SGPP1 and PLPP3 may hinder the recruitment of immune cells to the tumor environment, resulting in the blockage of cancer cell clearance and a subsequent poor prognosis." (PMID 34235182, 2021). "In summary, we found that low mRNA expression of SGPP1 and PLPP3 correlates with worse prognosis in patients with BC, particularly in those with TNBC, and that high expression of both of these genes may promote the infiltration of immune cells, especially DCs, into the tumor microenvironment." (PMID 34235182, 2021).
cancer (8 papers, 2014 to 2023). A tumor composed of atypical neoplastic, often pleomorphic cells that invade other tissues. "SGPP1 is an endoplasmic reticulum enzyme that dephosphorylates sphingosine-1-phosphate and has been shown to mediate cancer progression." (PMID 37316699, 2023). "Both in vivo and in vitro studies have identified SGPP1 and Smad2 as two novel targets of miR-27a, which is linked to STAT3 to regulate cancer cell proliferation, apoptosis and migration." (PMID 25166914, 2014). "SGPP1 is a tumor suppressor gene that plays a crucial role in cancer invasion and metastasis." (PMID 36059802, 2022). "S1P degradation enzymes, SGPP1, SGPP2 andSGPL1 are enzymes that metabolize S1P in the cell and their importance comes from their role in controlling the levels of S1P in the cell, excessive concentrations of which are detrimental to cell fate and functions as well as drug resistance and cancer." (PMID 26485657, 2015).
infection (3 papers, 2022 to 2025). The state of being infected such as from the introduction of a foreign agent such as serum, vaccine, antigenic substance or organism. "Our qRT-PCR data revealed that sphingolipid metabolic key genes encoding enzymes: Cers2, Gba2, Gla, Asah1, Asah2, Acer2, Acer3, Neu3, Sgpp1, and Sphk1 were robustly upregulated in mRNA levels by the infection of C. sinensis." (PMID 36339341, 2022). "Not only did the RNAseq experiment confirm our RT-qPCR results (i.e., upregulation of SPHK1 and SPHK2 but also SGPL1 and SGPP1), but also revealed regulation of additional SL metabolism genes upon infection, in addition to a vast array of inflammatory mediators." (PMID 40249190, 2025). "Therefore, we next tested whether an additional upregulation of SGPP1 could be responsible for maintaining S1P levels unaltered by counteracting the effects of SPHK1 upregulation upon Ctr infection." (PMID 40249190, 2025). "The result showed that during ALV-J infection, the levels of ASAH1, NAAA, CHKA, PGS1, SGPP1, DEGS2, and SMPD1 genes were significantly increased with infection time." (PMID 38598912, 2024). "Whereas, in PMNs the response to the Ctr infection is characterized by a strong upregulation of SPHK1, at both early (2 h) and late (24 h) infection time points, in M2Φ two counteracting pathways involving upregulation of SPHK1 as well as SGPP1 and SGPL1 likely maintain a steady pool of S1P." (PMID 40249190, 2025).
SGPP1 also shares sentences with these, for which no sentence is quoted: colitis (2 papers); Multiple Myeloma (2); allergic disease (1); colon cancer (1); colorectal (1); colorectal adenocarcinoma (1); coronary artery disease (1); hematological malignancies (1); lung carcinoma (1); oral squamous cell carcinoma (1); prostate carcinoma (1); psychiatric diseases (1); pulmonary fibrosis (1); schizophrenia (1); type 2 diabetes (1).